CASP8 (caspase 8)
Diseases named in the same sentence as CASP8 in open-access papers (continued):
Sharing a sentence is not in itself a finding about the gene and the disease.
infection (continued). "Caspase-8 is necessary for optimal production of inflammatory cytokines and host defense against infection by multiple pathogens including Yersinia, but whether this is due to death of infected cells or an intrinsic role of caspase-8 in TLR-induced gene expression is unknown." (PMID 27737018, 2016). "The kinetics of caspase-3 activation and of DNA fragmentation and loss are consistent, but we could not observe activation of caspase-8 and -9 before 8h of infection." (PMID 26513474, 2015). "Furthermore, molecular studies revealed that following infection of cells with CVB3, c-FLIPL associates with mitochondrial antiviral signaling protein (MAVS), increases caspase-8 activity and type I IFN production, and reduces viral replication, whereas c-FLIPS promotes the opposite phenotype." (PMID 24816846, 2014). "Consistent with this hypothesis, pre-treatment of macrophages with caspase-8 inhibitor (IETD) abolished caspase-3 activity following infection by both WT and yopK mutant Y. pestis suggesting caspase-8 is absolutely required for caspase-3 activation following Y. pestis infection." (PMID 23633954, 2013). "This situation has been previously reported in mollusks, with up-regulation of the caspase-8 gene in abalones after an experimental infection with a bacterial suspension and in crustaceans (L. vannamei), with an increase of caspase-3 expression after infection with Vibrio alginolyticus." (PMID 21347300, 2011). "Time course studies of rVSV infection pointed to a consecutive activation of intrinsic MOMP-caspase-9 signaling, as well as caspase-8-mediated extrinsic apoptosis, both leading to caspase-3/7 effector functions." (PMID 40896365, 2025). "This suggests that CMT-93 cells lack expression of key anti-apoptotic factors that suppress caspase-8 activation and sensitise CMT-93 cells to necroptosis during ΔespL infection, akin to our observations in unprimed macrophages." (PMID 40128366, 2025). "Even infection with the RIPK1-activating pathogen, Yersinia pseudotuberculosis, results in enhanced RIPK1–caspase-8 activation and enhanced secondary NLRP3 activation." (PMID 40053580, 2025). "Caspase-6 induces the cleavage of caspase-8 to form a positive feedback loop, promoting intrinsic apoptosis; increased caspase-8 and caspase-9 cleavage have both been reported in WT EMCV infections." (PMID 39928567, 2025). "As expected, infection with ΔM36 MCMV or ΔM36, M45mutRHIM MCMV (lanes 3, 4, 8, and 9) stimulated more robust cleavage of caspase-8 and -3 than WT or M45mutRHIM MCMV (lanes 2, 5, 7, and 10)." (PMID 38191748, 2024). "In murine models of infection, Yersinia blockade of NF-κB signaling triggers cell-extrinsic apoptosis through Receptor Interacting Serine-Threonine Protein Kinase 1 (RIPK1) and caspase-8, which is required for bacterial clearance and host survival." (PMID 39186805, 2024). "Using immunoblotting-based biochemical analyses, we observed IAV-induced PANoptosis in BMDMs at both 12 and 24 h post-infection, as indicated by activation of CASP1, gasdermin D (GSDMD) and GSDME, along with CASP8, CASP3, and CASP7, as well as MLKL." (PMID 38005819, 2023). "Following infection with C. burnetii expressing BlaM-0077, we observed that the percentage of T4SS-injected cells was also significantly decreased in Casp8−/−Ripk3−/− cells treated with rTNF, similarly to WT BMDMs." (PMID 37461589, 2023). "Following infection, direct activation of RIPK3 mediates recruitment of FADD, RIPK1 and MLKL to drive both MLKL induced necroptosis and RIPK3/Caspase-8 mediated apoptosis." (PMID 36175538, 2023). "Casp1–/– BMMs retain the ASC to caspase-8 pathway; and indeed, we observed weak caspase-8, BID, and caspase-3 cleavage at 4 hr post-infection (hpi), indicating that this pathway is relatively slow." (PMID 38055781, 2023).
infection (continued). "We infected BMDMs of C57BL/6, Gsdmd−/−, Casp8/RIPK3−/−, and Casp8+/+/RIPK3−/− mouse strains with B. abortus, and after 17 h of infection, we evaluated the secretion of IL-1β in the supernatant of the cells." (PMID 36532444, 2022). "Although we did not investigate cell recruitment in this study, we hypothesize that innate cells recruitment to the site of infection may be impaired by the absence of pyroptosis in caspase-8 deficient animals, which could in part explain the increased bacterial load observed in these animals." (PMID 36532444, 2022). "We found that the expression of several molecules was upregulated following infection with C. parvum in HCT-8 cells, including FasL, TRAIL, Apaf-1, and Caspase-8." (PMID 35974384, 2022). "At 24 hr post infection, LDH levels in supernatant, cell viability (n=3) (G) and cleavage of GSDME, caspase-1, caspase-3, and caspase-8 were measured in ZIKV-infected JEG-3 cells." (PMID 35972780, 2022). "Interestingly, inhibition of apoptotic pathways appears to permit HSV-induced necroptosis in astrocytes that is independent of ZBP1, as treatment with a pan caspase or a caspase-8 inhibitor did not reduce levels of phosphorylated MLKL following infection in ZBP1-deficient cells." (PMID 35549723, 2022). "Agreeing with previous reports, infection with SARS-CoV-2 for 48 hr induced caspase-3 and caspase-8 activation in immortalized simian kidney epithelial Vero CCL81 and human lung epithelial Calu-3 cell lines." (PMID 35666101, 2022). "Furthermore, we observed here that mice deficient for caspase-8 and GSDMD are more susceptible to Brucella infection in vivo compared to wild type animals, suggesting that pyroptosis triggered during B. abortus infection is an important mechanism to control infection." (PMID 36532444, 2022). "Activation of CASP8 is tightly regulated by RIPK1, which showed decreased expression levels in response to infection with either isolate." (PMID 36298696, 2022). "(A) Immunoblot of caspase-8 and caspase-3 cleavage in Calu-3 and Vero CCL81 cells in response to infection with SARS-CoV-2 for 48 hr (CoV2, detected with rabbit anti-Spike), UV irradiation (UV), or freezing and thawing (F/T)." (PMID 35666101, 2022). "mRNA expression levels of caspase-8 and receptor-interacting kinase-3 (RIPK3) were upregulated >10-fold after infection." (PMID 35215199, 2022). "Expression of caspase-8 can also trigger the formation of ASC and activation of caspase-1 in case of pathogen infection." (PMID 34122107, 2021). "Caspase-8 has also been found to control cytokine expression independently of RIP3, and is necessary for host defense against pathogen infection and controlling TLR-induced cytokine production independent of cell death." (PMID 34887869, 2021). "Other studies have found that the induction of apoptosis by SARS-CoV-2 infection requires caspase 8, as caspase 8 inhibitors greatly reduce BID cleavage, caspase-3 activation, and PARP-1 cleavage upon infection with SARS-CoV-2." (PMID 33499234, 2021). "To this end, our RT-PCR results were in agreement with the microarray data and we observed differential expression of caspase-1, caspase-4, and caspase-8 and NLRP3 in MDR-PA induced infection." (PMID 35046947, 2021). "Since coactivation of TLRs and TNFR can likely occur during pathogen infection in vivo, engagement of TNFR induces cleavage of N4BP1 by caspase-8 to allow TRIF-independent TLRs to enhance cytokine responses." (PMID 33785842, 2021). "Herein, the expression of CASP8, CASP7, and CASP 3 was significantly up-regulated after infection, with the expression of TNFα significantly up-regulated at 6 and 24 h post-infection." (PMID 34451461, 2021). "Our assessment of MCMV-infected myeloid or non-myeloid cells reinforces evidence that vICA suppression of CASP8 activation and apoptosis acts against TNF-dependent signaling during infection." (PMID 33126536, 2020).
infection (continued). "CASP8, as well as cFLIPL and RIPK1, emerge to be central cell autonomous innate pathogen sensors such that levels of all these proteins increase during infection." (PMID 33126536, 2020). "When Triton-X-soluble fractions were evaluated, levels of unprocessed CASP8 (p55), cFLIPL (p55), and RIPK1 (p75) all increased during infection with either virus." (PMID 33126536, 2020). "CMV replication and infection require a complex interplay between an innate cytokine (TNF), cell autonomous mediator of extrinsic death (CASP8), and vICA-dependent subversion of the host inflammatory signaling." (PMID 33126536, 2020). "All pro- (Casp-8, FADD, BAX, and BAK) or anti-apoptotic (BCL-2 and XIAP) genes tested were down regulated at early time points post-SVA infection (2–4 h p.i.)(p < 0.05 when compared to mock-infected cells)." (PMID 30918505, 2019). "Activation of caspase-8, -9, and -10 was observed in the wild-type ZJO-infected cells after 2 h of infection, while the Δval1686 strain was unable to induce these initiator caspases." (PMID 29252102, 2018). "We treated FHM cells with inhibitors against caspase-8 and -9 (Q-IETD-Oph and Q-LEHD-Oph) for 1 h prior to infection and then measured nuclear fragmentation and caspase-3 activity." (PMID 29252102, 2018). "In a shock-like infection induced by a virulent ehrlichial pathogen, IFNα/β-induced BM failure and hematopoietic suppression via increased RIPK1 activation and diminished caspase 8 expression." (PMID 30080899, 2018). "RIPK1 was cleaved in cells infected with HRV16, however, in contrast to the 38 kDa product produced by caspase 8 cleavage, a c-terminal 23 kDa cleavage product is produced during HRV16 infection." (PMID 29371673, 2018). "Considering the induction of apoptosis, the pbMEC of the high responder group also showed significantly stronger induction of the pro-apoptotic genes Bax, FAS, CASPASE 8, and CASPASE 3 post-infection, as compared to the low responder group." (PMID 29187202, 2017). "In aggregate, these results provide evidence that NC/99 infection activates parallel pathways downstream of the sensor protein DAI, the RIPK3–MLKL-dependent necroptosis pathway, as well as the RIPK3-caspase 8-mediated apoptosis pathway." (PMID 29203926, 2017). "They demonstrate that during infection of macrophages with virulent M. tuberculosis, a complex of RIPK1/RIPK3/pro-caspase-8 translocates to the mitochondria." (PMID 28892415, 2017). "Thus, we investigated whether caspase-8 is activated during infection." (PMID 28771586, 2017). "We found that A172, SK-N-SH and RD cells shared the same apoptotic pathways, with caspase 3, caspase 8 and caspase 9 all being activated after CA16 infection." (PMID 25350381, 2014). "Several apoptosis-related molecules such as caspase 3, caspase 8, caspase 9, and BAX appeared to be induced under conditions of reduced IFIT3, and the expression of these molecules was further enhanced by DV infection." (PMID 24223959, 2013). "Twenty-four hours after infection, strong upregulation was assayed in NOS2, Mapk11, CASP8 and Casp3 genes." (PMID 22280251, 2012). "Various caspases, including the subfamily of inflammatory mediator (CASP1, CASP4), the apoptotic activator (CASP2, CASP8) and the apoptotic executioner (CASP7) were up-regulated in response to infection." (PMID 21110886, 2010). "By contrast, and as would be predicted if caspase 8 were essential for both HIV-induced apoptosis and HIV replication, infection of I9.2 cells resulted in less death and less viral replication." (PMID 19287489, 2009). "Through TUNEL assay, flow cytometry, and apoptotic pathway analysis, Our analysis revealed that H5N6 AIV infection markedly upregulates apoptotic genes such as Fas, FADD, caspase-8, BAK, cytochrome c, APAF1, caspase-9, and caspase-3 (P < 0.05), thereby promoting apoptosis in DEFs." (PMID 41992349, 2026).
infection (continued). "Moreover, the in vitro porcine alveolar macrophage model can only simulate local infection, and the regulatory mechanism of the MEG3/ssc-miR-135/CASP8 axis during systemic infection requires further evaluation in animal models or using different cell lines." (PMID 41156747, 2025). "During infection, ZBP1 responds to IAV and forms the ZBP1-RIPK3 complex, which then facilitates recruitment of RIPK1 and further forms ZBP1-PANoptosomes with ZBP1/RIPK3/RIPK1/FADD/CASP8 as the main components." (PMID 40568592, 2025). "The predominance of caspase-8 (without releasing IL-1β and IL-18) reshapes inflammatory responses and cell death mechanisms during infection." (PMID 41208996, 2025). "Caspase-8, which is recruited and activated by auto-phosphorylated RIPK1 to drive apoptosis, was only partially cleaved and not fully processed into its active form in Rickettsia-infected cells, even during the late stages of infection." (PMID 40607949, 2025). "This is achieved through the inhibition of Fas clustering at the cell membrane during infection, resulting in the lack of caspase-8 activation." (PMID 41204030, 2025). "We found that the inflammation/infection-induced HSPC necroptosis and BM failure in Casp8−/− mice can be completely prevented by Ripk3 deletion; however, the HSC self-renewal defects of Casp8−/− HSCs is mediated by Ripk1-Tbk1-Ifnβ signaling independent of Ripk3." (PMID 38637559, 2024). "ST7 infection causes a reduction in the activity of caspase 3 and caspase 9, but not caspase 8 after 6 and 12 h of infection." (PMID 39338600, 2024). "M36 vICA-mediated caspase-8 suppression unleashes necroptosis during infection; whereas, HCMV vICA does not." (PMID 39772130, 2024). "PPV infection induced a significant increase in p-RIPK3 and p-MLKL 24 h post-infection when apoptosis was inhibited; however, the expression and cleavage of Caspase-8 was not changed." (PMID 39614405, 2024). "Accordingly, infection or cellular stressors can lead to cell death by the combinatory crosstalk of pyroptotic, apoptotic, and necroptotic molecules (like ZBP1, RIPK1, RIPK3, CASP1, CASP8, and NLRP3, MLKL, and GSMDs) to effectively control pathogenic invasion." (PMID 38590437, 2024). "Casp1/11–/–Casp8+/–Ripk3–/– mice retain Caspase-8 function downstream of both NLRC4 and TNFα and based on our previous experiments with Casp1/11–/– mice, we expected that these mice would be resistant to infection." (PMID 36645406, 2023). "After infection with JEV, the gene transcription levels of caspase-3 and caspase-8 showed an upward trend in both normal cells and BAK.KD cells, but whether this is related to JEV-induced apoptosis needs further verification." (PMID 37112954, 2023). "Our data also indicate that caspase-8 autocleavage is not involved in control of in vitro or in vivo infection, suggesting that caspase-8 is promoting cell death and bacterial restriction independently of its apoptotic activity." (PMID 37279255, 2023). "After infection with A. hydrophila, the transcriptional levels of TLR1, TLR2, caspase 8, MyD88, FADD, TOLLIP isoform 1 and TOLLIP isoform 2 were all significantly up-regulated in the kidney, indicating that bacterial infection induced the activation of TLR signaling pathway in the yellow catfish." (PMID 37056759, 2023). "At 9h and 24h post-infection (multiplicity of infection; MOI 10), the distinctive cytopathic effect (round cells/detached cells), due to HSV-1 replication, was detected in the wild type cells expressing caspase-8 (CASP8+/+), while the CASP8-/- cells showed a less evident cytopathic effect." (PMID 35853963, 2022). "Results from a time-course infection in THP-1 cells showed a different cleavage pattern of caspase-8 in absence of Us11 protein." (PMID 35853963, 2022). "This evidence indicates that during infection, even in absence of Us11, the first cleavage step of caspase 8 occurs and generates the p43/41 fragment." (PMID 35853963, 2022).
infection (continued). "However, caspase-8 is not required for Salmonella-induced cell death at 2, 6, and 24 h post-infection using an MOI of 1 or 10, showcasing the variability of the roles of caspase-8 within the programmed cell death response." (PMID 35563804, 2022). "Deletion of RIPK3 is not sufficient to protect cells from death during this infection, while the combined deletion of caspase-8/RIPK3 does prevent cell death." (PMID 35563804, 2022). "Moreover, H37Rv infection increased the expression of the molecules involved in the necroptotic pathway, such as ASK1, p-38, RIPK1, RIPK3, and caspase-8, while H37Ra increased caspase-8 and decreased RIPK3 at the transcriptional level." (PMID 35631013, 2022). "Similar to the phenotype observed in Casp8/Ripk3/Casp1/11−/− mice, B. thailandensisvgrG5ΔCTD infection was also attenuated in mice lacking caspase-1/11 or GSDMD." (PMID 34154417, 2021). "Following infection with SRV-8, the autophagic proteins LC3 and p62/SQSTM1 interacted with procaspase-8, which might be responsible for the activation of the caspase-8/-3 cascade and apoptosis in SRV-8-infected Jurkat cells." (PMID 32244330, 2020). "This was consistent with the observation that the combined loss of caspase-8 and RIPK3 did not impair bacterial control in vivo until at least 3 weeks post-infection." (PMID 32735843, 2020). "Recent studies have also demonstrated that caspase-8 is upregulated during infection-induced inflammasome activation in the absence of either caspase-1 or GsdmD21." (PMID 31209224, 2019). "The results obtained at 8, 24 and 72 h were 13.9% ± 0.33%, 4.24% ± 0.59% and 9.37% ± 1.43% (data not shown), respectively, which allowed us to conclude that caspase 8 activation peaked after 1h of infection." (PMID 31035520, 2019). "No evident change in caspase-8 and caspase-9 occurred in cells at 48 h post-infection compared to mock-infected cells." (PMID 30670030, 2019). "Recent studies revealed caspase-8 upregulation during infections in the absence of either caspase-1 or GsdmD21." (PMID 31209224, 2019). "The upregulation of viral cleavage of RIPK1 with caspase 8 activation was not seen in the infection models." (PMID 29371673, 2018). "In addition, previous studies using the Salmonella enterica serovar Typhimurium have indicated that both caspase-8 and caspase-1 are recruited to the ASC puncta in response to infection." (PMID 28771586, 2017). "Infections in macrophages from littermate control mice indicated that caspase-8 activation occur in Casp1/11-/-, but not in Casp1/11+/- and Casp1/11+/+ macrophages." (PMID 28771586, 2017). "We, therefore, tested whether caspase-8 and caspase-3 were cleaved to generate the active forms after C. albicans infection in PBMO and CBMO 2 h after infection." (PMID 27870876, 2016). "Strikingly, five days post-infection, we found a significant defect in the percentage of TNF and IL-6 positive Ripk3-/-Casp8-/- inflammatory monocytes isolated from the mesenteric lymph nodes (mLN) of mixed BM chimeras compared with either wild-type or Ripk3-/- cells from the same animal." (PMID 27737018, 2016). "Ripk3-/-Casp8-/- mice exhibit severely diminished cytokine responses following infection by a number of gram-negative bacterial pathogens, including Yersinia, in contrast to Ripk3-/- mice, which have no discernible defect." (PMID 27737018, 2016). "Infection with Salmonella enterica serovar Typhimurium (S. Typhimurium) triggers the formation of a complex inflammasome that can include NLRC4, NLR family PYRIN domain-containing protein 3 (NLRP3), ASC, caspase-1 and caspase-8 (refs 5, 17, 18, 19)." (PMID 27670879, 2016). "The delayed activation of caspase 8 (as compared to caspase 9) would also support activation of this pathway through TRAIL, which showed significant levels of expression only after 24 hours infection." (PMID 24034452, 2013). "Moreover, infection of dendritic cells with Yersinia leads to the formation of a FADD/caspase-8/RIP1 complex and caspase-8 activation." (PMID 23226685, 2012).